S100B (S100 calcium binding protein B)
Diseases named in the same sentence as S100B in open-access papers (continued):
Sharing a sentence is not in itself a finding about the gene and the disease.
schizophrenia (continued). "We demonstrated that the serum activity of LE and a1-PI, and antibodies to the protein S100B and MBP may be related to the diagnosis of schizophrenia, which confirms the data obtained earlier by us." (PMID 34025476, 2021). "Also we investigated associations between some immunological patterns and markers of inflammatory response (CRP, IL-2, IL-6, IL-10, the activity of LE and a1-PI, antibodies to S100B and MBP) with clinical symptoms in schizophrenia." (PMID 34025476, 2021). "An increase in plasma S100β levels shows a positive correlation with the occurrence of negative symptoms of schizophrenia and cognitive disorders." (PMID 32121669, 2020). "The level of S100B was increased by almost two times compared to the healthy control groups, but its increase was observed in schizophrenia patients is not uniform." (PMID 32116664, 2019). "Further, the negative symptoms of the patients with schizophrenia have been found to correlate with increasing S100B serum levels." (PMID 28373983, 2017). "That is to say that the micromolar S100B concentrations seen in clear neuronal damage (e.g. after traumatic brain injury or infarction) do not seem applicable to schizophrenia." (PMID 28358925, 2017). "In sum, our meta-analyses indicate higher S100B serum levels in schizophrenia when compared to control subjects without any evidence for treatment effects to date." (PMID 26941608, 2016). "Though many effects of S100B have been explored, the pathophysiologic role of elevated S100B levels in schizophrenia is not yet clarified." (PMID 27013967, 2016). "Meta-regression analyses revealed significant effects of illness duration and clinical symptomatology, in particular the total score of the Positive and Negative Syndrome Scale (PANSS), on serum S100B levels in schizophrenia." (PMID 26941608, 2016). "Based on these data, one might conclude that serum S100B represents a biomarker for white matter tracts and, consequently, oligodendroglia, which might have led to the association between white matter parameters and schizophrenia in our study, without relevant effects on gray matter." (PMID 27013967, 2016). "Corresponding authors were contacted in cases where S100B levels or patient characteristics for schizophrenia-only patients were not explicitly stated in the original article." (PMID 26941608, 2016). "Last but not least, when interpreting results on S100B concentrations and schizophrenia a number of limitations should be considered." (PMID 25202915, 2014). "In another study, a small sample of patients with schizophrenia had higher levels of S100B in cerebrospinal fluid (CSF) but not serum (after Bonferroni correction)." (PMID 24358202, 2013). "Data showed raised serum levels of S100B in schizophrenia female patients, but not male patients, compared to controls." (PMID 23705829, 2013). "We discuss innate inflammation-related CNS abnormalities—including glial pathology, elevated cytokines levels, cyclooxygenase activation, glutamate dysregulation, increased S100B levels, increased oxidative stress, and BBB dysfunction—in MDD, BPD, schizophrenia, and OCD." (PMID 23547920, 2013). "Prothrombotic State: Schizophrenia cases showed higher PAI-1 levels (P = .006) that were not correlated with S100B." (PMID 20631894, 2010). "In contrast, circulating S100B levels in schizophrenia subjects were neither correlated with the BMI (drug free: r = −0.108, P = .751; with drug: r = −0.007, P = .981) nor with levels of leptin, HGF and resistin." (PMID 20631894, 2010). "From a mechanistic point of view, S100B released by activated astrocytes binds to RAGE, triggering downstream inflammatory cascades involving NF-κB and MAPK pathways, which contribute to perpetual neuroinflammation and oxidative stress in schizophrenia, similar to mechanisms observed in AD." (PMID 40650013, 2025).
schizophrenia (continued). "Although there is controversy about the validity of S100B, an acidic calcium-binding protein secreted by astrocytes and oligodendrocytes, as a marker of BBB disruption, there have been reports of higher serum and CSF S100B concentrations in patients with schizophrenia compared to controls." (PMID 39858403, 2024). "Meta-regression analyses revealed significant effects of illness duration, with higher S100B serum levels in the disorder’s course, and an impact of clinical symptomatology, in particular a negative correlation of the total score of the PANSS with serum S100B levels in schizophrenia." (PMID 26941608, 2016). "Other investigations suggesting an absence of elevated S100B in schizophrenia are limited." (PMID 24358202, 2013). "In conclusion, previous findings support the hypothesis that S100B is involved in the pathogenesis of schizophrenia, but elevated levels of this protein may not exclusively reflect brain- or glial-specific pathologies." (PMID 20631894, 2010). "Our results confirm elevated S100B serum levels as an indicator of glial pathology in schizophrenia, although this finding does not seem to be disease-specific, i.e., serum S100B seems to be elevated also in other psychiatric disorders such as mood disorders, as shown in recent meta-analyses." (PMID 26941608, 2016). "Therefore, biomarker values of S100B is not specific to diagnosis of schizophrenia, but may be a potential factor to predict symptoms’ severity and degree of brain damage and glial dysfunction." (PMID 27279465, 2016). "The clinical implications of this study are two-fold, firstly that S100B levels may no longer be considered as a biomarker that is dependent on neurological function alone, and secondly, that regulating metabolic dysfunction in schizophrenia may represent a novel drug target." (PMID 23705829, 2013).
Cognitive impairment (51 papers, 2009 to 2026). Abnormal cognition is characterized by deficits in thinking, reasoning, or remembering. "Five studies examined neurone specific enolase and S100b, which are implicated in neuronal cell death, and three reported associations with cognitive impairment." (PMID 39668510, 2025). "Higher S100B levels were linked to longer HF duration (p = 0.014) and increased left atrial volume index (p = 0.041), but also with a higher prevalence of mild cognitive impairment (p = 0.023) and lower visual/verbal memory scores (p = 0.006)." (PMID 39201780, 2024). "Notably, higher S100B levels were associated with a higher prevalence of mild cognitive impairment (MCI; 69% vs. 50%) and lower visual/verbal memory T-scores." (PMID 39201780, 2024). "Notably, higher S100B levels were associated with a higher prevalence of mild cognitive impairment (MCI) and lower scores in visual/verbal memory tests." (PMID 39201780, 2024). "This would be consistent with observations from other research teams, which showed that significant increases in S100B levels in patients with end-stage renal disease (compared to a control group) are associated with complications of the disease, such as cognitive impairment." (PMID 39519343, 2024). "In addition, they found that a higher S100-b concentration at baseline was associated with poorer memory function and less subjective cognitive impairment at 5 and 30 days of follow-up." (PMID 34679338, 2021). "S100B is considered a plasma biomarker in traumatic brain injury, and cerebral small vessel disease, in which it is associated with cognitive impairment in patients." (PMID 30410436, 2018). "In diabetic models, rats have been reported to exhibit increased protein expression of both GFAP and S-100β; however, reduced GLT-1 expression was associated with an increased risk of postoperative cognitive impairment in diabetic mice." (PMID 41462586, 2025). "Elevated levels of inflammatory markers, such as S100β, have also been associated with BBB dysfunction in patients with cognitive impairment." (PMID 40336917, 2025). "Higher baseline S100B was correlated with poorer memory function at 30 days follow-up, but also with less subjective cognitive impairment and better response to treatment." (PMID 37759935, 2023). "S100-β and NSE levels were elevated in the early phase of neuronal damage and were linked with subsequent cognitive impairment." (PMID 36148077, 2022). "This preliminary finding is even more relevant for future clinical applications if we consider the previous work which has shown S100β protein in CSF EV fractions isolated from patients with cognitive impairment." (PMID 34639196, 2021). "S100β is a biomarker involving in the mechanism of cognitive impairment, which existed in several types of cell in the peripheral and central nervous system [CNS]." (PMID 34425851, 2021). "Among them, mice overexpressing S100b show enhanced excitotoxicity, altered synaptic plasticity, and cognitive impairment." (PMID 34417446, 2021). "There is substantial evidence suggesting that early AD patients have elevated S100B levels, leading to cognitive impairment." (PMID 32112645, 2020). "Comparison of serum S100B level between mild cognitive impairment and moderate-severe cognitive impairment group, *P<0.05 represents that the difference was statistically significant." (PMID 32112645, 2020). "The serum S100B levels in the moderate to severe cognitive impairment group were lower than those in mild cognitive impairment group (P<0.05)." (PMID 32112645, 2020). "As cognitive impairment has been shown to be associated with S100 proteinin several diseases including mild traumatic brain injury, chronic cerebral hypoperfusion, and Parkinson’s, wereasonably hypothesize that the S100β protein is associated with cognitionimpairment in SVD patients." (PMID 28143956, 2017).
Cognitive impairment (continued). "S100b increases the free calcium concentration in neurons; whereas mice overexpressing S100b show enhanced excitotoxicity, altered synaptic plasticity and cognitive impairment." (PMID 26916334, 2016). "For example, S100b is elevated after cardiac surgery and correlated with post-operative cognitive impairments." (PMID 27922822, 2016). "Recent reports by others have shown that in patients affected by senile dementia, one of the early markers of cognitive impairment is the presence of antibodies directed against S100B." (PMID 23483891, 2013). "The relationship between S100B levels and cognitive impairment suggests that this biomarker may reflect both acute neuronal injury and chronic neurodegenerative processes linked to diabetes." (PMID 41150802, 2025). "High S100B levels reflect ongoing neurodegeneration and may correlate with cognitive deficits and other neuropsychiatric symptoms seen in AUD." (PMID 38928583, 2024). "Importantly, an animal study suggested that S100B emanated primarily from the brain during endotoxemia and played a pivotal role in acute brain injury and long-term cognitive impairment." (PMID 38274881, 2023). "We did not see any differences in the neurotrophic markers, which could explain cognitive impairment when delivering at lower GA, but the higher levels of growth factors and S100B could indicate a less mature body and brain." (PMID 34631615, 2021). "However, the cognitive implications of S100B are not limited to T2DM: studies have shown that this protein is involved in cognitive impairment in a variety of diseases, including cerebral small vessel disease and AD." (PMID 32112645, 2020). "Besides, serum S100B levels were lower in the type 2 diabetes patients with impaired cognition than in those with normal cognition." (PMID 32112645, 2020). "A recent study showed that the increased of serum S100B and E-selectin levels could predict long-term cognitive impairment in critically ill patients." (PMID 32382007, 2020). "Our study found that serum S100B levels were positively correlated with cognitive function in T2DM patients with cognitive impairment, which suggests that S100B may be involved in the emergence and progression of cognitive dysfunction in T2DM." (PMID 32112645, 2020). "Our conclusion suggests that S100B may play a neuroprotective role against the emergence and progression of cognitive impairment in T2DM." (PMID 32112645, 2020). "Besides, CSF GFAP and S100B levels could serve as predictors of cognitive impairment and would decline with cognitive ability in PD patients." (PMID 40702763, 2025). "Therefore, we speculate that S100B exerts a neuroprotective effect against cognitive impairment in T2DM." (PMID 32112645, 2020). "Higher serum S100B levels may be peripheral biochemical marker for cognitive impairment in COPD." (PMID 24359080, 2013). "Higher serum S100B level may be the peripheral biochemical marker for cognitive impairment in COPD." (PMID 24359080, 2013). "NSE, S100β, and GFAP are considered to negatively correlate with TBI severity and prognosis, and to represent cognitive deficits." (PMID 36034283, 2022). "Comparison of clinical data, biochemical indicators, S100B levels and RBANS scores between the mild cognitive impairment group and the moderate to severe cognitive impairment group." (PMID 32112645, 2020). "Previous studies have shown increased concentration of protein levels of systemic S-100β and HMGB-1, and their pivotal role in surgery-induced cognitive deficits." (PMID 26225860, 2015). "Subjects with HIV-associated neurocognitive disorders had higher abundance of CSF extracellular vesicles and proteins related to synapses, glial cells (incl., GFAP, S100B), inflammation, and stress responses vs. patients without cognitive impairment." (PMID 33115334, 2021).
Cognitive impairment (continued). "S100β is usually elevated in the blood and cerebrospinal fluid following nervous system damage during BBB impairment, which has been considered as a biomarker of cognitive impairment." (PMID 34248475, 2021). "Thus, the increase in BDNF levels, the decrease in S100B, and the absence of cognitive deficit can be explained by the potentiation of this pathway." (PMID 33019732, 2020). "In addition, we found that the levels of serum S100B in patients with cognitive impairment in T2DM were negatively correlated with the progression of the disease, suggesting that S100B may undergo changes during the emergence and progression of cognitive impairment in T2DM." (PMID 32112645, 2020). "Furthermore, levels of several amyloid-β forms, but not human Tau or S100-β, were significantly correlated with self-reported cognitive impairment 18 months after ICU discharge, whereas inflammatory markers were not correlated to impaired long-term cognitive function." (PMID 22206727, 2011). "The presence of S100B at the level of CS100B ≥ 7.8 pg/mL was surprisingly detected in few patients in the NfT2DM group before COVID-19 (1.96%) and after COVID-19 (10.9%), which might be due not so much to their pharmacotherapy but to the absence of cognitive impairments." (PMID 39519343, 2024).
cardiac arrest (48 papers, 2008 to 2026). Cessation of breathing and/or cardiac function. "Increased levels of S100β in the peripheral blood have been suggested to indicate an increased permeability of the blood–brain barrier and found to be associated with neurotrauma, cerebral ischemia, cardiac arrest, and cardiac surgery." (PMID 32245513, 2020). "Thus, brain ischemia or any other extra-cranial origin may be the cause of S100B elevation in cardiac arrest." (PMID 36832309, 2023). "Established biomarkers such as neuron-specific enolase (NSE), S100 protein B (S-100B), and the cytokine interleukin-8 (IL-8) are used for prognostication after cardiac arrest." (PMID 37373829, 2023). "Neuron-specific enolase (NSE) and S-100b have been used to assess neurological damage following out-of-hospital cardiac arrest (OHCA)." (PMID 33411836, 2021). "In studies of patients after cardiac arrest, determination of S100B concentration on admission, i.e., within 8 h after successful cardiopulmonary resuscitation (CPR), was a good predictor of 24-hour mortality." (PMID 32575870, 2020). "S100B levels are subject to extracranial sources as well which presents limitations in multi-trauma patients and post cardiac arrest patients." (PMID 28035993, 2016). "In the area of cardiac arrest, elevated S100B levels in patients correlate with severity of neurologic injury with persistently elevated levels >0.414 ng/mL at 72 h predicting mortality with 100% specificity." (PMID 28035993, 2016). "We have recently shown that combining serum levels of S100B and bispectral index monitoring accurately predicts outcome after cardiac arrest." (PMID 25886727, 2015). "Several approaches have been shown to have a prognostic value several days after cardiac arrest, such as assessment of serum markers of brain injury (neuron-specific enolase, S-100B), electroencephalography, somatosensory evoked potentials, and neuroimaging." (PMID 23036303, 2012). "Concerning reliable biochemical markers of brain tissue damage, increased serum levels of the low molecular weight protein S100B have been reported after cardiac arrest correlating with neurological complications." (PMID 20158893, 2010). "Two previous studies have focused on the effect of therapeutic hypothermia on levels of serum S-100B protein in survivors of cardiac arrest." (PMID 19368739, 2009). "Beside clinical evaluation, biochemical markers (neuron-specific enolase, protein S100B) and electrophysiological studies (somatosensory-evoked potentials) are established tools for outcome prediction in patients after cardiac arrest." (PMID 18554414, 2008). "S100β and neuron-specific enolase (NSE) proteins, which are specific proteins originating from neurons, can be used as neurobiochemical markers because they are linked to stroke, traumatic brain injury, cardiac arrest, and brain damage after CPB." (PMID 38414171, 2024). "According to an article that investigated neurocognitive function and biochemical markers after cardiac surgery, medical conditions such as paralysis, subarachnoid hemorrhage, head trauma, CPB, and coma after cardiac arrest can lead to an increase in serum S100β protein." (PMID 38414171, 2024). "S100B is a glia-specific protein, and an established peripheral biomarker of CNS injury, and has been shown to predict neurologic outcomes after resuscitation of cardiac arrest and ECMO patients." (PMID 35288822, 2022). "This study aimed to determine whether the combination of procalcitonin (PCT) and S100B improves prognostic performance compared to either alone in cardiac arrest (CA) patients treated with targeted temperature management (TTM)." (PMID 30732223, 2019). "Furthermore, CO was observed to lower S-100B levels; S-100B refers to a marker of neurological outcomes after cardiac arrest." (PMID 30158958, 2018).